GCM2 (GCM transcription factor 2)
Diseases named in the same sentence as GCM2 in open-access papers (continued):
Sharing a sentence is not in itself a finding about the gene and the disease.
breast carcinoma (3 papers, 2021 to 2025). "In this study, we demonstrated that circulating methylated GCM2 and TMEM240 provide high diagnostic accuracy, sensitivity, and specificity for monitoring breast cancer progression." (PMID 40691650, 2025). "For example, hypermethylated circulating glial cells missing transcription factor 2 (GCM2) has been reported as a noninvasive breast cancer-specific biomarker in both TCGA data and Taiwanese breast cancer patients, across all major breast cancer subtypes." (PMID 40691650, 2025). "Significant differences in the validation set of samples were found for seven genes; the combination of the four genes GCM2, ITPRIPL1, CACNA1E, DLGAP2 (AUC = 0.99) showed the highest diagnostic value based on logistic regression for all breast cancer samples." (PMID 37628841, 2023). "We hypothesized that tumor burden in breast cancer patients could be dynamically assessed by monitoring circulating methylated GCM2 and TMEM240 following treatment." (PMID 40691650, 2025). "The data indicated that the aberrant circulating hypermethylated CCDC181, GCM2 and ITPRIPL1 detected in the plasma samples were also significantly present in the associated tumor tissues of breast cancer patients (Spearman’s rho = 0.702, 0.497 and 0.634, all p < 0.001)." (PMID 33803633, 2021). "Hypermethylation of CCDC181 and GCM2 could be detected in ductal carcinoma in situ (DCIS) tumors of breast cancer patients." (PMID 33803633, 2021). "Following surgery in breast cancer patients, there is a significant decrease in circulating methylated GCM2, indicating that circulating GCM2 levels in breast cancer patients could serve as novel biomarkers for posttreatment monitoring, aiding in the detection of residual tumors." (PMID 40691650, 2025). "This study investigates the potential of circulating methylated GCM2 and TMEM240 as biomarkers for noninvasive monitoring of breast cancer progression." (PMID 40691650, 2025). "The plasma of patient H223 demonstrated increases in the abnormal methylation levels of circulating GCM2 and TMEM240 as her breast cancer progressed and decreases when the patients receive adequate treatment." (PMID 40691650, 2025). "To assess the cutoff value for detecting circulating methylated GCM2 and TMEM240 in plasma for predicting tumor progression, we employed a training group comprising 14 Eastern European and 152 Taiwanese breast cancer patients." (PMID 40691650, 2025). "Aberrant methylation patterns of the CCDC181, GCM2, ITPRIPL1, ENPP2, LOC643719, ZNF177 and ADCY4 genes were identified and further evaluated in paired tumor and normal tissues of breast cancer patients." (PMID 33803633, 2021). "Most breast cancer-specific circulating methylated CCDC181, GCM2 and ITPRIPL1 biomarkers were found in the plasma." (PMID 33803633, 2021). "Aberrant methylation patterns of the CCDC181, GCM2 and ITPRIPL1 genes are highly prevalent in Western and Taiwanese breast cancer patients, suggesting that they are potential biomarkers for early prediction in Western and Asian countries." (PMID 33803633, 2021). "The methylation patterns of the CCDC181, GCM2, ITPRIPL1, ENPP2, LOC643719, ZNF177 and ADCY4 genes were further determined in plasma samples from healthy and early breast cancer patients." (PMID 33803633, 2021). "Combined analysis of CCDC181, GCM2 and ITPRIPL1 was performed by Recursive Partitioning and Regression Trees (RPART) using 57 breast cancer and 134 health plasma samples from the subjects." (PMID 33803633, 2021). "Combined analysis of high specificity breast cancer biomarker GCM2 and ITPRIPL1 can improve the sensitivity and specificity for breast cancer prediction." (PMID 33803633, 2021). "The breast cancer specificity of methylated CCDC181, GCM2, ITPRIPL1, LOC643719 and ZNF177 ranged from 64.3 to 100%, indicating lower false-positive signals." (PMID 33803633, 2021).
breast carcinoma (continued). "Circulating methylated CCDC181, GCM2 and ITPRIPL1 was detected in 57.1–84.6% of ductal carcinoma in situ (DCIS) tumors from breast cancer patients." (PMID 33803633, 2021). "The heatmap revealed hypermethylation of CCDC181, GCM2 and ITPRIPL1 in tumors of breast cancer patients compared with adjacent normal tissues from the Taiwanese and TCGA cohort (respectively)." (PMID 33803633, 2021). "Aberrant methylation of CCDC181, GCM2, ITPRIPL1, ENPP2, LOC643719, ZNF177 and ADCY4 was found in breast cancer patients from the Taiwanese and TCGA cohorts using the methylation array." (PMID 33803633, 2021). "In this study, we carry out automatic detection of circulating cell-free methylated DNA, including GCM2, ITPRIPL1 and CCDC181, and find a pattern that can detect early breast cancer more accurately compared with currently used biomarkers." (PMID 33803633, 2021). "As promising biomarkers, circulating methylated CCDC181, GCM2 and ITPRIPL1 are expected to improve the detection of breast cancer." (PMID 33803633, 2021). "Hypermethylation of CCDC181, GCM2 and ITPRIPL1 was observed in different subgroups of breast cancer patients, including in individuals of different races and in various menopause states as well as with different tumor stages and histological types." (PMID 33803633, 2021). "The box plot demonstrates an increase in CCDC181, GCM2 and ITPRIPL1 in tumors of Taiwanese breast cancer patients compared with the adjacent normal tissues using the paired-sample Wilcoxon test (Z score −9.02, −7.94, −8.65, p < 0.001)." (PMID 33803633, 2021). "Few studies have reported the clinical significance and application of aberrant CCDC181, GCM2 and ITPRIPL1 methylation in breast cancer." (PMID 33803633, 2021). "Therefore, this study aimed to evaluate the potential of the simultaneous plasma detection of methylated GCM2 and TMEM240 in improving the prediction of residual disease and tumor progression in breast cancer patients." (PMID 40691650, 2025). "Additionally, the methylation levels of GCM2 and TMEM240 can also reflect the treatment status of breast cancer patients in real time." (PMID 40691650, 2025). "To further determine the methylation pattern of breast cancer tissues in the Taiwanese cohort, we analyzed the methylation levels of CCDC181, GCM2, ITPRIPL1, ENPP2, LOC643719, ZNF177 and ADCY4 in tumors and adjacent normal tissue in Taiwanese breast cancer patients." (PMID 33803633, 2021). "Hypermethylation of CCDC181, GCM2 and ITPRIPL1 was found in more than 80% of patients with lower tumor histologic grades, and in 70% of early-stage breast cancer among all subtypes of breast cancer patients." (PMID 33803633, 2021). "Therefore, the profiles of CCDC181, GCM2 and ITPRIPL1 in breast cancer were selected for further analysis." (PMID 33803633, 2021). "The results for seven candidate genes—CCDC181, GCM2, ITPRIPL1, ENPP2, LOC643719, ZNF177 and ADCY4—were successfully validated by sequencing and stable detection in ccfDNA from the plasma of Taiwanese patients with breast cancer." (PMID 33803633, 2021). "Circulating methylated CCDC181, GCM2 and ITPRIPL1 analysis could be combined with ultrasound to facilitate the early detection of breast cancer." (PMID 33803633, 2021). "Finally, the most breast cancer-specific biomarkers, circulating methylated CCDC181, GCM2 and ITPRIPL1 (CGIm), were identified in patients with early-stage breast cancer." (PMID 33803633, 2021). "The aberrant methylation patterns of the CCDC181, GCM2 and ITPRIPL1 genes means that they are potential biomarkers for the detection of early BC and can be combined with breast imaging data to achieve higher accuracy, sensitivity and specificity, facilitating breast cancer detection." (PMID 33803633, 2021).
breast carcinoma (continued). "To further investigate whether the use of circulating methylated CCDC181, GCM2 and ITPRIPL1 biomarkers could improve the detection of breast cancers, we combined the ultrasonography BI-RADS (3 and 4a) and circulating methylated CCDC181, GCM2 and ITPRIPL1 levels." (PMID 33803633, 2021). "Therefore, we suggested that the methylation pattern of circulating CCDC181, GCM2 and ITPRIPL1 could be combined with mammography or/and ultrasonography and applied for the early prediction of breast cancer." (PMID 33803633, 2021). "Overall, detecting methylated GCM2 and TMEM240 in plasma offers a novel, accurate, and noninvasive method for monitoring breast cancer progression." (PMID 40691650, 2025).
hyperphosphatemia (3 papers, 2020 to 2024). Abnormally high level of phosphate in the blood. "Moreover, hyperphosphatemia in glial cells missing homolog 2 (Gcm2) null mice and the addition of phosphate to osteoblast cultures did not result in increased Fgf23 transcripts, a result that was also found in other studies." (PMID 33716961, 2021).
parathyroid carcinoma (3 papers, 2021 to 2022). "This is consistent with our finding of expression of variant GCM2 in both familial and sporadic parathyroid carcinoma with increased ability to stimulate PTH transcription." (PMID 35038313, 2022).
autoimmune disease (1 paper, 2021). A disorder resulting from loss of function or tissue destruction of an organ or multiple organs, arising from humoral or cellular immune responses of the individual to their own tissue constituents. "Assessment of anti-calcium sensing receptor (CaSR) antibodies and genetic testing for Glial Cell Missing-2 (GCM2) would also be appropriate to do to rule out autoimmune disease, due to its high prevalence in hypoparathyroidism." (PMID 35036185, 2021).
autosomal dominant hypocalcemia (1 paper, 2025). Autosomal dominant hypocalcemia (AD hypocalcemia) is a disorder of calcium homeostasis characterized by variable degrees of hypocalcemia with abnormally low levels of parathyroid hormone (PTH) and persistent normal or elevated calciuria. "In Western cohorts, CASR gain-of-function mutations are among the most frequently reported causes of autosomal dominant hypocalcemia, whereas GCM2 mutations are relatively rare but have been described in Latin American and South Asian families, sometimes linked to founder effects." (PMID 41155848, 2025).
breast tumors (1 paper, 2021). "The data suggested that methylated circulating CCDC181, GCM2 and ITPRIPL1 were mostly derived from primary tumors and could serve as new postsurgical monitoring biomarkers for the detection of residual tumors, with the exception of primary breast tumors." (PMID 33803633, 2021).
endometriosis (1 paper, 2016). The growth of functional endometrial tissue in anatomic sites outside the uterine body. "This indicates that the study of GCM1 and GCM2 in endometriosis should be carried out using highly sensitive methods and possibly during the development of the disease to catch the transient presence of their transcripts." (PMID 27886257, 2016).
familial hypoparathyroidism (1 paper, 2024). A rare heterogeneous group of metabolic disorders characterized by abnormal calcium metabolism due to deficient secretion of parathormone (PTH), without other endocrine disorders or developmental defects. "Testing for mutations in genes associated with familial hypoparathyroidism, such as CaSR, GCM2, or PTH, should be considered to rule out an inherited etiology." (PMID 39416579, 2024).
invasive ductal carcinoma (1 paper, 2025). "Additionally, GCM2 is frequently hypermethylated across both histological subtypes—such as invasive ductal carcinoma and invasive lobular carcinoma—and molecular subtypes, including luminal A, luminal B, HER2-enriched, and triple-negative breast cancer." (PMID 40691650, 2025).
parathyroid disease (1 paper, 2022). "Furthermore, our studies suggest that activating GCM2 variants may contribute to facilitating more aggressive parathyroid disease." (PMID 35038313, 2022).
secondary hyperparathyroidism (1 paper, 2019). Overproduction of parathyroid hormone in response to influence external to the parathyroid glands. "This may explain the elevated expression of Gcm2 in secondary hyperparathyroidism." (PMID 30677043, 2019).
tumor (6 papers, 2013 to 2025). "Five genes demonstrated complete loss or downregulation of expression in at least 20% of RCC tumours (GCM2 (80% of RCC), RGS7 (46.7%), TMEM74 (46.7%), NEFM (20%) and AEBP1 (20%))." (PMID 24034811, 2013). "In addition, Cluster 4 and 6 revealed no apparent driver mutation but showed aberrant expression of some tumor-related genes, such as GCM2 and AXIN1, indicating that driver gene plays an important, but not indispensable, role in the initiation of PA." (PMID 34054720, 2021). "The level of methylation in four genes—PRDM14, CACNA1E, CCDC181, and GCM2—correlated with tumor size." (PMID 37628841, 2023). "In our study, we used a set of 96 tumor samples of less than 2 cm; in this set, the assessment of the methylation of the GCM2, ITPRIPL1, CACNA1E, and DLGAP2 genes most accurately distinguished cancer from healthy tissues." (PMID 37628841, 2023). "Correlation analysis showed that the methylation of the PRDM14, CACNA1E, CCDC181, and GCM2 genes correlated with tumor size." (PMID 37628841, 2023). "Performance metrics such as sensitivity, specificity, and accuracy were averaged to ensure robustness, supporting the use of combined GCM2 and TMEM240 for monitoring treatment response and tumor burden." (PMID 40691650, 2025). "To further determine the origin of circulating methylated CCDC181, GCM2 and ITPRIPL1, we analyzed whether the DNA methylation between plasma and matched tumor tissues showed a similar pattern." (PMID 33803633, 2021).
cancer (4 papers, 2022 to 2025). A tumor composed of atypical neoplastic, often pleomorphic cells that invade other tissues. "PTH, GCM2, SYN, CgA, GATA3, and CAM5.2 are always positive in cancer cells, while TTF1, PAX8, CAL, and TG are always negative." (PMID 38019325, 2023).
GCM2 also shares sentences with these, for which no sentence is quoted: DiGeorge syndrome (2 papers); adenoma (1); Autoimmune polyendocrinopathy-candidiasis-ectodermal dystrophy (1); colorectal cancer (1); deafness (1); esophagus cancer (1); Fibroadenoma (1); gastric cancer (1); hypophosphatasia (1); invasive lobular carcinoma (1); liver cancer (1); lung carcinoma (1); metabolism (1); neonatal severe hyperparathyroidism (1); neurodegenerative disease (1); ovarian carcinoma (1); pancreatic cancer (1); parathyroid benign tumors (1); pituitary disease (1); pituitary tumor (1); preeclampsia (1); rickets (1); thyroid tumor (1); triple-negative breast carcinoma (1); uterine cancer (1).